BRCA2 (BRCA2 DNA repair associated)
Diseases named in the same sentence as BRCA2 in open-access papers (continued):
Sharing a sentence is not in itself a finding about the gene and the disease.
breast cancer (continued). "We examined an institutional cohort of breast cancer patients with germline BRCA1 (n=46) and BRCA2 (n=35) mutations and found that FOXC1 expression on immunohistochemical staining is associated with BRCA1 vs BRCA2 mutations [30/46 vs. 6/35]." (PMID 27708239, 2016). "From genetically derived cancers (estimated to account for some 5 to 10 % of all cancers) only about 1 % represents gastric carcinomas, 3–5 % for colorectal cancers, and about 8 % for breast cancers (breast cancer 1, early onset = BRCA1 or breast cancer 2, early onset = BRCA2)." (PMID 27053248, 2016). "Secondary aims of the study are to investigate whether the intervention will lead to a reduction of breast cancer incidence and breast cancer mortality in BRCA1 and BRCA2 mutation carriers." (PMID 27473440, 2016). "We have previously shown that breast cancer cell lines show differences in the HR capacity although they share no common mutations in BRCA1 or BRCA2." (PMID 26799421, 2016). "Mutations in BRCA2 were detected in 2.6 % of patients with familial breast cancer and were absent in those with early-onset disease and familial breast and ovarian cancer." (PMID 27553291, 2016). "However, mutations in the two major breast cancer susceptibility genes BRCA1 and BRCA2 explain only 15–20% of all familial BC/OC cases." (PMID 27504877, 2016). "To date, BRCA1 and BRCA2 mutations in breast cancer patients have not been characterized in the Uzbek population." (PMID 29138730, 2016). "In breast cancer cells, BRCA2 directly binds to nucleophosmin and ROCK2 at centrosomes; the dysfunction of BRCA2, which accounts for the majority of heredity breast and ovarian cancer, causes aberrant centrosome amplification and a high frequency of multinucleated cells." (PMID 26725045, 2016). "BRCA1 and BRCA2 mutations in breast cancer patients have not been characterized in the Uzbek population." (PMID 29138730, 2016). "BRCA1 and BRCA2 genes explain a large part of hereditary breast cancer." (PMID 27129401, 2016). "Statistical analysis of the methylation profiles of FOXO3 promoter in these familial breast cancers revealed that FOXO3 methylation levels were significantly higher in BRCA1-mutated tumours, compared with BRCA2-, BRCAx- and BRCA2/x-mutated tumours (P=0.019, P=0.053 and P=0.026, respectively)." (PMID 27043660, 2016). "Also included are breast cancer susceptibility proteins, such as BRCA1 (FANCS) and BRCA2 (FANCD1), and SLX4 (FANCP), a scaffold for endonucleases such as XPF (FANCQ)." (PMID 27760317, 2016). "Using PCR, PAGE, Sanger sequencing, and statistical analyses, we compared VNTR genotypes in the XRCC5 promoter between healthy individuals and three types of familial breast cancer cases: mutated BRCA1 (BRCA1+), mutated BRCA2 (BRCA2+), and wild-type BRCA1/BRCA2 (BRCAx)." (PMID 27148484, 2016). "The risk of CIA in young patients with breast cancer (≤47 years) does not appear to be related to BRCA1 or BRCA2 mutation status." (PMID 27234217, 2016). "We demonstrated that BRCA1-deficient secretome proteins could cluster most human BRCA1- and BRCA2-related breast carcinomas at the transcriptome level." (PMID 27566577, 2016). "Moreover, our previous study demonstrated that the combined expression pattern of PARP1, γH2AX, BRCA1, and BRCA2 is very helpful in the prediction of the prognosis of breast carcinoma." (PMID 27643881, 2016).
breast cancer (continued). "Pancreatic and male breast cancers were significant for BRCA2." (PMID 26047126, 2015). "Mammographic density is a strong and independent risk factor for breast cancer, reported to exceed all other risk factors apart from age and the presence of mutations in high penetrance breast cancer predisposition genes such as BRCA1 and BRCA2." (PMID 26110820, 2015). "Therefore, it’s necessary to further elucidate the relevance of rs3803662 to breast cancer risk with BRAC1 and BRCA2 mutation." (PMID 26239137, 2015). "There is no demonstrated benefit for primary chemoprevention of breast cancer in BRCA1 or BRCA2 mutation carriers (I,A)." (PMID 26669313, 2015). "Conversely, an interaction between rs299290 and rs11649877 (3’ region of TUBG1) could increase breast cancer risk in both BRCA1 and BRCA2 mutation carriers (HRs = 1.33 and 1.21, respectively)." (PMID 25830658, 2015). "For example, we did not have information on BRCA1 and BRCA2 mutations, family history of breast cancer, and occupations before or after military service." (PMID 26376727, 2015). "In the Breast Cancer Prevention Trial, healthy women with a BRCA2 mutation receiving tamoxifen had a reduction of breast cancer by 62 %, an effect not seen among those with a BRCA1 mutation, but the overall number of individuals was very small." (PMID 26669313, 2015). "Today, it is established that BRCA1- and BRCA2-associated breast cancers are not phenotypically identical." (PMID 25925750, 2015). "Because the most important function of BRCA2 is DNA repair in the nuclei, another possibility is that the splice variant lacking exons 14–16 is associated with mammary tumors." (PMID 26202431, 2015). "Additionally, we observed different associations of rs3803662 with breast cancer risk based on different ER subtype and BRCA1/BRCA2 mutation carriers." (PMID 26239137, 2015). "The association we observed among BRCA2, but not BRCA1, mutation carriers may reveal a functional alteration that would be specific to mechanisms involving BRCA2-related breast cancer." (PMID 25925750, 2015). "It was recently shown that haplogroup H was more frequent in BRCA2 carriers whereas haplogroup X was more frequent in BRCA1 carriers compared to patients not carrying BRCA mutations among Italian familial breast cancer cases." (PMID 25783644, 2015). "In the present study, a case–control GWA study for breast cancer risk was carried out in a large collection of Sardinian breast cancer patients negative for BRCA1 or BRCA2 mutations." (PMID 25956309, 2015). "PARP1 inhibitors are used to treat breast cancer exhibiting deletion of BRCA1 or BRCA2." (PMID 25872931, 2015). "They demonstrated that, breast cancer cells containing germ line mutations in BRCA1 and BRCA 2 genes become sensitized to PARP inhibitors in a PARP1 dependant manner and lose sensitivity to PARP inhibition on regaining BRCA2 functionality." (PMID 25606064, 2015). "Currently the major genes known to influence breast cancer risk is BRCA1 and BRCA2." (PMID 26010605, 2015). "In a prospective study of 2,483 women with BRCA1 or BRCA2 mutations, no breast cancers were diagnosed in the women who underwent RRM during 3 years of prospective follow-up." (PMID 26557407, 2015). "Immunohistochemistry was used to examine the expression of PARP1 and BRCA1/BRCA2 in breast cancer." (PMID 25865228, 2015). "In this study, the entire coding sequence of the CHEK2 gene was screened for mutation on 59 breast cancer patients who were non-BRCA1 and BRCA2 mutation carriers and two previously reported missense mutations, p.I160M and p.R180C were identified in two unrelated breast cancer patients." (PMID 25629968, 2015).
breast cancer (continued). "All tumours were derived from Caucasian patients diagnosed with breast cancer lacking any known germ-line mutations in BRCA1 or BRCA2." (PMID 26300993, 2015). "Over 60% were diagnosed at Stage I (30.2%) or II (31.7%); 64.8% did not know their breast cancer subtype; and 64.4% did not know their breast cancer susceptibility gene mutation (BRCA1 or BRCA2) carrier status." (PMID 25853030, 2015). "For this purpose, we sequenced the complete coding and flanking regulatory regions of PALB2 from constitutional DNA of 152 patients with hereditary predisposition to breast cancer, all previously employed to study the distribution of germline mutations in BRCA1, BRCA2." (PMID 26489409, 2015). "Higher frequency (P < 0.001) of autoantibodies to BRCA2 was found in breast cancer sera." (PMID 25865228, 2015). "In Finland, recurrent mutations explain most of the familial breast cancer risk caused by the currently known susceptibility genes, such as BRCA1, BRCA2, PALB2, and CHEK2, whereas in other more diverse populations several rare mutations in each gene have been identified." (PMID 25918678, 2015). "A pioneering breakthrough in SL-based cancer therapy showed that inhibition of poly (ADP-ribose) polymerase (PARP) in cancer cells that harbour loss-of-function events in the breast-cancer susceptibility genes BRCA1 and BRCA2 is dramatically lethal to these cells." (PMID 26427375, 2015). "A large fraction of these susceptibility alleles are associated with increased risk in persons with a family history of breast cancer despite the absence of mutations in BRCA1 or BRCA2, accounting for about 30 % of the familial risk of the disease." (PMID 25956309, 2015). "The ‘normal’ samples were tumour-associated normal breast tissue removed at the time of definite surgery in the Caucasian patients diagnosed with breast cancer lacking any known germ-line mutations in BRCA1 or BRCA2." (PMID 26300993, 2015). "However, we still need to elucidate the mechanisms that regulate BRCA2 expression levels, and how low BRCA2 expression leads to the development of canine mammary tumors." (PMID 26202431, 2015). "Importantly, there is evidence that tamoxifen decreases risk of primary breast cancer as well as contralateral breast cancer for BRCA1 and BRCA2 mutation carriers." (PMID 26496879, 2015). "The study reported a 62% reduction in breast cancer with prophylactic tamoxifen in healthy BRCA2-mutation carriers, but there was no reduction in breast cancer incidence among women with an inherited BRCA1 mutation." (PMID 26557407, 2015). "With regard to the results obtained for BRCA2 mutation carriers, the opposite direction of the potential association with ERα-negative breast cancer compared with the association observed for BRCA1 mutation carriers is intriguing." (PMID 25830658, 2015). "An interaction between rs299290 and rs6064391 (in intron 2 of CSTF1) could reduce breast cancer risk in both BRCA1 and BRCA2 mutation carriers (interaction HRs = 0.87 and 0.73, respectively)." (PMID 25830658, 2015). "This region was chosen because splice variants have been detected for a homologous region in human BRCA2, and we speculated that canine mammary tumors might show a similar result." (PMID 26202431, 2015). "In addition, higher frequency (P < 0.01) of autoantibodies to PARP1 and BRCA2 was found only in breast cancer sera." (PMID 25865228, 2015). "Further studies will also be needed to determine whether such BRCA1/BRCA2 mutational differences contribute directly or indirectly to the biological differences between BRCA1 and BRCA2 breast cancers." (PMID 25699710, 2015).
breast cancer (continued). "The current study is the first study performing mutation analyses in BRCA1, BRCA2 and PALB2 and determining the frequency of CHEK2 c.1100delC in triple negative and/or premenopausal breast cancer patients in South Africa through both next generation sequencing and large rearrangement testing." (PMID 26577449, 2015). "This approach is justified since post-menopausal breast cancer accounts for two-thirds of breast cancer cases amongst high risk women (with a 16-40% lifetime risk), 40% of cases amongst BRCA1 carriers and 50% of cases amongst BRCA2 carriers." (PMID 25648828, 2015). "In total, 108 South African breast cancer patients underwent mutation screening using a Next-Generation Sequencing (NGS) approach in combination with Multiplex Ligation-dependent Probe Amplification (MLPA) to detect large rearrangements in BRCA1 and BRCA2." (PMID 26577449, 2015). "Given that both half-sisters previously had uninformative (negative) BRCA1 and BRCA2 testing, a multigene panel that included other breast cancer predisposition genes was offered and completed." (PMID 26484312, 2015). "We have conducted such a case–control GWA study for breast cancer risk in our collection of Sardinian breast cancer patients who are negative for BRCA1 or BRCA2 mutations." (PMID 25956309, 2015). "In this study, we found reduced BRCA2 mRNA expression levels in canine mammary tumors." (PMID 26202431, 2015). "Clinical testing could also be considered in the context of another BRCA2-related malignancy, and when at least one family member is diagnosed with premenopausal breast cancer." (PMID 25225577, 2014). "In BRCA2 carriers, four of the variants lacking evidence of association with overall breast cancer were associated with ER-negative and three with ER-positive breast cancer." (PMID 25919761, 2014). "In the current study, patient SM-46, who was found to carry an exon 4 deletion in the ATM gene, also had a pathogenic mutation in the BRCA2 gene; therefore, the involvement of the ATM intragenic deletion with breast cancer predisposition in this particular case remains to be clarified." (PMID 24884479, 2014). "However, several breast cancer susceptibility genes identified so far, such as BRCA1 and BRCA2, account for only less than 5% of the total breast cancer incidence." (PMID 25559835, 2014). "This would explain why the breast cancer risk modification due to rs1466785 would only be detected in the context of BRCA2 mutation carriers and not in the general population." (PMID 24698998, 2014). "These predictors would be useful in genetic counseling and decision-making for a genetic test but they are still of limited value since a considerable number of BRCA1 or BRCA2 mutations are observed in breast cancer families without such risk factors." (PMID 24591761, 2014). "We evaluated whether differences in associations of known breast cancer susceptibility variants between BRCA1 carriers, BRCA2 carriers and the general population are mediated by tumor ER status in mutation carriers." (PMID 25919761, 2014). "Of all women with breast cancer, 5 to 10% may have a germline mutation of the genes BRCA1 and BRCA2." (PMID 25184114, 2014). "Women with mutations in BRCA1 or BRCA2 gene are 3 to 7 times more likely to develop breast cancer than the women without mutations in those genes, with excessive relative risks of about 30-fold for early onset diseases (before the age of 45)." (PMID 24711893, 2014). "Indeed, PSC in many ways can mimic epithelioid mesothelioma, but unlike mesothelioma, PSC is linked to hereditary and sporadic mutations of two breast cancer susceptibility genes (BRCA-1 and BRCA-2)." (PMID 24910640, 2014).
breast cancer (continued). "Although they had been selected based on their evidence of association with breast cancer risk, under the initial hypothesis they are also plausible modifiers of ovarian cancer risk for BRCA1 and BRCA2 mutation carriers." (PMID 24698998, 2014). "Only SNPs in the known breast cancer susceptibility loci FGFR2 and TOX3 were associated with non-TN breast cancer in BRCA2 carriers, and none were associated with TN breast cancer at P <10−6." (PMID 25919761, 2014). "BRCA2 and Rad51 expression were proposed as histologic criteria in canine breast cancer staging." (PMID 24641873, 2014). "In contrast, BRCA2 mutation-associated breast tumors are not described to favor the development of any particular histopathological subtype of breast cancer." (PMID 24959366, 2014). "We conducted analyses of large pathology datasets accrued by the Consortium of Investigators of Modifiers of BRCA1/2 (CIMBA) and the Breast Cancer Association Consortium (BCAC) to reassess previously reported histopathological predictors of BRCA1 and BRCA2 mutation status." (PMID 25857409, 2014). "We compared HRs for the association with overall breast cancer and ER-positive and ER-negative breast cancer for all the 74 known breast cancer susceptibility variants between BRCA1 carriers, BRCA2 carriers and population-based studies using published data from BCAC." (PMID 25919761, 2014). "Thus, the activity of flavonoids was clearly dependent on BRCA2 dysfunction and represents a new clinical application for BRCA2 mutant in breast cancer." (PMID 24317580, 2014). "Many common breast cancer susceptibility alleles identified through population-based genome-wide association studies (GWASs) have also been associated with breast cancer risk in BRCA1 and BRCA2 carriers." (PMID 25919761, 2014). "Family history of breast cancer, early age at diagnosis, characteristics of the first primary (for example lobular histology and stage) and mutations in specific genes, including BRCA1, BRCA2 and CHEK2, are considered as risk factors." (PMID 25277819, 2014). "Soon after the identification of the breast cancer predisposition genes BRCA1 and BRCA2, mutation screening of families burdened with a substantial history of breast and ovarian cancer, became a routine demand, since it aids the identification of individuals at high risk." (PMID 24695549, 2014). "The minor allele of NEIL2-rs1466785 was associated with increased breast cancer risk in BRCA2 mutation carriers; moreover, when considering the genotype-specific risks observed that the best fitting model was the dominant one." (PMID 24698998, 2014). "Interestingly, monoallelic mutations in some of the downstream proteins are known to confer a high risk of breast cancer (e.g., FANCD1 = BRCA2, FANCN = PALPB2, FANCJ = BRIP1, FANCO = RAD51C)." (PMID 26567103, 2014). "While the degree of breast cancer susceptibility is still unclear, some studies examining recurrent PALB2 mutations tested in patients unselected for family history have demonstrated a risk and penetrance as high as those arising from BRCA2 mutations." (PMID 25225577, 2014). "Array Comparative Genomic Hybridization (CGH) has been shown as an effective method to identify BRCA1-mutated breast cancers and sporadic cases with a BRCA1-like profile for appropriate chemotherapeutics, and to distinguish BRCA2-mutated tumors from sporadic breast tumors." (PMID 25857409, 2014). "In addition, it has been reported that BRCA2-related breast cancers are less likely to over express HER2 receptor compared to sporadic cancers." (PMID 25093046, 2014). "Interestingly, the proportion of ER-negative breast cancers among BRCA1-likeCGH and BRCA2-likeCGH breast cancers was similar to that reported for BRCA1-mutated and BRCA2-mutated breast cancers, respectively." (PMID 24887359, 2014).